EGFR (epidermal growth factor receptor)
Diseases named in the same sentence as EGFR in open-access papers (continued):
Sharing a sentence is not in itself a finding about the gene and the disease.
tumor (continued). "A key point in this study is that five (15.2%) of these EGFR mutations have been detected in patients where it was not possible to perform the mutational study in tissue, either because of the clinical situation or because of tumor locations not accessible to biopsy." (PMID 36497340, 2022). "Afatinib inhibited tumor growth in GCPDX models through EGFR amplification, EGFR overexpression, or HER2 amplification." (PMID 35664756, 2022). "Immunohistochemical results of the tumor tissue show that the expression levels of Ki67 and MMP9 as well as EGFR were significantly reduced in CA-treated groups compared with the CA-untreated group." (PMID 35645793, 2022). "All the synthesised thiazolyl-pyrazolines have been screened for their inhibitory activities against EGFR and VEGFR-2 kinases and for their cytotoxic effect against nine cell lines derived from five tumour subpanels." (PMID 36000167, 2022). "Similar to EGFR, insulin-like growth factor type 1 receptor (IGF-1R) and platelet-derived growth factor receptor (PDGFR) also play a major role in tumor development and progression." (PMID 35241721, 2022). "Tumor Immune Microenvironment (TIME) alterations have been examined before and after the development of EGFR-TKI resistance." (PMID 35264191, 2022). "In pancreatic cancer, cooperation of Hh and EGFR signaling induced high-level expression of SOX2 that promoted both tumor initiation and tumor growth." (PMID 36118530, 2022). "In contrast to RPTEC, global EGFR and MET activities showed less activity in the FLCN-negative UOK257 tumor cell line when compared with the FLCN-restored UOK257-2, even though EGFR and MET emerge as significantly important pathways in each cell model." (PMID 35863698, 2022). "PD-L1 overexpression is promoted by oncogenic and constitutive activation signals, including EGFR, Kirsten rat sarcoma virus oncogene homolog (KRAS), and protein kinase B (AKT), which are mechanisms of cell-intrinsic tumor resistance." (PMID 35222387, 2022). "In our previous study, we constructed a recombinant EGFR/CD13 dual-targeting fusion protein, which exhibited anti-tumor efficacy." (PMID 35416106, 2022). "Afa irreversibly binds to pan-ErbB tyrosine kinases, such as EGFR, HER2, and HER3, and, thus, exhibits anti-tumor efficacy by inducing cancer-cell apoptosis." (PMID 36145507, 2022). "To try to understand the mechanisms, we detected the expression of phospho-EGFR, -HER2, -IGF-1R, -AKT, and -ERK as well as their total protein levels in the xenograft tumor tissues by western blot analysis." (PMID 36142299, 2022). "Circulating tumor cell (CTC) numbers were correlated with treatment response and EGFR exon 20 p.T790M." (PMID 36292049, 2022). "Vandetanib is an oral inhibitor of vascular endothelial growth factor receptor 2 (VEGFR-2), epidermal growth factor receptor (EGFR), and Ret tyrosine kinases involved in tumor growth, progression, and angiogenesis." (PMID 35835754, 2022). "Studies conducted on mice showed a tumor regression after dual blockade of BRAF and EGFR using vemurafenib and cetuximab." (PMID 36556139, 2022). "NGS analysis and subsequent qRT-PCR analysis suggested that blocking IKK potentiates EGFR inhibition at least partially though the suppression of NF-κB/RELA-dependent transcription of tumorigenic genes and induction of tumor suppressors." (PMID 36358633, 2022). "This exPKM2 facilitates tumor angiogenesis, cancer cell migration via the phosphoinositide-3-kinase/protein kinase B (PI3K/Akt) and Wnt/β-catenin pathways, and proliferation via EGFR activation." (PMID 35256696, 2022). "Erlotinib, a targeted inhibitor of epidermal growth factor receptor pathway, lacks FDA approval in HNSCC due to inadequate tumor response." (PMID 36110959, 2022). "Other than that, EGFR and other RTKs activate JAK‐STAT3 and other pathways to confer the tumour cells resistance to apoptosis." (PMID 35692096, 2022).
tumor (continued). "Osimertinib, a third-generation, irreversible EGFR–TKI, at either 25 mg/kg daily or 12.5 mg/kg daily exhibited minimal anti-tumor activity, with TGI of 24% and 4%, respectively." (PMID 36551608, 2022). "Targeted therapy is designed to interfere with critical biological pathways (such as RTK/RAS/MAP-Kinase pathway and I3K/Akt signaling) and block dysregulated proteins (such as EGFR and BRAF) which play essential roles in tumor formation, growth, and invasion." (PMID 36059550, 2022). "Distributions of tumor MGMT status and EGFR, TERT, and IDH1 genomic alterations observed in the current study are consistent with those reported in the current literature." (PMID 34510238, 2022). "To further determine the potential role of CAFs in EGFR TKIs resistance development, we analyzed the proportion of CD45+/CD90+ cells subpopulation, which is identified as CAFs, in tumor tissues from EGFR TKIs sensitive/resistant NSCLC patients." (PMID 35831824, 2022). "In summary, we found that ST3GAL6-AS1 positively regulates ST3GAL6 in LUAD cells, while the depletion of ST3GAL6-AS1 activates the EGFR signaling pathway, upregulates the expressions of MMP2 and 9, and promotes the invasion of LUAD tumor cells." (PMID 36092699, 2022). "Here, the authors show that an antibody drug conjugate-like compound targeting both EGFR and HER2 overcomes gemcitabine resistance in PDAC preclinical models by mechanisms involving the tumour suppressor SMAD4." (PMID 36127339, 2022). "Overall, these results indicated that anti-EGFR CAR1-T and CAR2-T cells had a strong cytotoxic activity against ESCC, leading to tumor elimination." (PMID 36551506, 2022). "Among these, EGFR and MSLN specific CAR T cells seem to be more promising compared to others due to the antigen's higher specificity and lower on‐target, off‐tumor toxicity concern." (PMID 35844304, 2022). "Both hu-αEGFR-172 and hu-EGFR(ACVC)-172 markedly inhibited tumor growth and extended the survival of mice bearing the B16F10-EGFR tumors." (PMID 36442099, 2022). "Pathological features that specialists were most unsure of included CDX2 status, EGFR status, Lymph node ratio, KRAS status, BRAF status and tumour budding." (PMID 35323316, 2022). "ID-1 can activate EGFR pathways that promote resistance to TMZ chemotherapy, resulting in tumor recurrence with ID-1-enriched cells after treatment." (PMID 35954407, 2022). "Aberrant activation of EGFR and MET signaling pathways drives tumor cell growth and proliferation in lung cancer." (PMID 36341333, 2022). "In this study, we identified Toll‐7 as a proto‐oncogene that promotes tumour growth and invasion by activating both Egr‐JNK and EGFR‐Ras signalling." (PMID 35050535, 2022). "Conversely, the loss of SIAH expression (SIAHLow/OFF) in residual tumors post-NACT/NST reflects EGFR/K-RAS pathway inactivation (OFF), indicating effective therapy and chemo-sensitive tumor cells." (PMID 36176751, 2022). "EGFR proved to be dysregulated in male NSCLC; the importance of this potential sex-related tumor particularity remains to be determined." (PMID 36556276, 2022). "EGFR inhibitors including gefitinib, erlotinib, and lapatinib have shown limited therapeutic efficacy for HNSCC patients due to tumor resistance." (PMID 35873484, 2022). "A trend or significant differences in PD‐L1 expression between different histologic types in NSCLC, different EGFR status, and different ALK status, and different tumor tissue storage time." (PMID 34841687, 2022). "To develop new anti-tumour reagents for the treatment of NSCLC, we are very interested in designing and synthesising new EGFR inhibitors." (PMID 35260020, 2022).
tumor (continued). "Other targeted therapies have been investigated in clinical trials in patients with advanced gastric cancer, including Cetuximab and Panitumumab in EGFR-positive tumor, or Rilotumumab and Onartuzumab in MET-positive tumor." (PMID 36230592, 2022). "Tumor growth is closely related to the epidermal growth factor (EGF) in urine, and the EGF receptor (EGFR) is highly expressed in tumor cells." (PMID 35872872, 2022). "Moreover, tissue and cellular distribution analyses demonstrated that the Ze affibody accumulated in HT29 tumor xenografts through binding to EGFR-expressing tumor cells, indicating that the Ze affibody could be used as a carrier for tumor cell-targeted delivery of PS." (PMID 35635308, 2022). "have developed a novel approach to target heterogeneous antigen expression in Glioblastoma tumours by using a CAR construct specific for EFGRVIII and a bispecific T‐cell engager (BiTE) specific for EGFR." (PMID 36495108, 2022). "Some miRNAs, such as let-7, miR-18a*, miR-30b, miR-143 and miR-145, have been shown to be tumor suppressors (since they inhibit KRAS expression) and potential biomarkers for predicting favorable responses to anti-EGFR therapy." (PMID 36230757, 2022). "Molecular testing showed EGFR amplification and -EML4-ALK fusion, the TMB was 1.6 muts/Mb and the tumor was PD-L1 positivewith a TPS of 3% on immunohistochemistry." (PMID 36523965, 2022). "The activation of JNK, either by EGFR or chemotherapy agent, stabilizes BMI1 and MCL1 protein expressions through suppressing HUWE1 expression, which then promote tumour initiation and chemo‐resistance." (PMID 35794816, 2022). "Our study further identified that the tumor suppressing function of FBXW2 was through its ubiquitylation and degradation of EGFR and hence targeting EGFR in PCa will be a good therapeutic strategy." (PMID 35499593, 2022). "Several researchers report that EGFR, Ras/MAPK, PI3K/Akt, Notch, Wnt/β-catenin, TGF-β, and Notch pathways all play important roles in the process of tumor drug resistance." (PMID 35684449, 2022). "Secondly, we narrowed down our search to four subgroup unions that had both Tumor Type (HNSC, LUAD, LUSC, or SKCM) and the EGFR WT gene." (PMID 36230688, 2022). "YAP/TAZ integrate various oncogenic signaling pathways such as EGFR, TGFβ, Wnt, PI3K, GPCR, and KRAS, and are instrumental for tumor initiation, progression, and chemoresistance." (PMID 35163776, 2022). "EGFR-TKIs strengthen MHC class I and II antigen presentation in response to IFN-γ, increasing T-cell-mediated tumor killing." (PMID 35742933, 2022). "TNBCs' are aggressive tumours with poor prognosis and have been reported to express High molecular weight cytokeratin (CK5/6, CK14 & CK17), epidermal growth factor receptor (EGFR), E-cadherin, and Androgen receptors (AR)." (PMID 35463732, 2022). "CXCL12, which was reported to induce EGFR-TKI resistance through CXCR7 in tumor cells through the ERK pathway, was decreased after EGFR-TKI treatment in our study." (PMID 36612121, 2022). "The EGFR blockade augments the antitumor T-cell responses subsequent to MHC classes I and II upregulation in tumor cells." (PMID 35062731, 2022). "Moreover, the decreased expression of TRPM6 in cancer patients treated with EGFR targeted therapies (e.g., cetuximab) seems to positively contribute to the oncologic efficacy of these therapies, as decreased magnesium availability inhibits cell proliferation and slows down tumor growth." (PMID 35551258, 2022). "Technically, CSP can be delivered into tumor cells by nanomaterials packaged with CSP mRNA and viral vectors carrying CSP protein, which sheds us new therapeutic strategies to overcome EGFR-TKI resistance in advanced NSCLC patient with EGFR mutant." (PMID 35186935, 2022). "Mechanistically, epithelial TGFβ signalling induces a growth-promoting EGFR-signalling module that synergises with mutant APC and KRAS to drive MAPK signalling that re-sensitise tumour cells to MEK and/or EGFR inhibitors." (PMID 36477656, 2022).
tumor (continued). "In this regard, SMART-Exos acted as a bridge between T cells and EGFR-expressing TNBC cells, recruiting T cells to tumour sites and activating their killing effect." (PMID 36167539, 2022). "Therefore, a profound study of the effect of each Src inhibitor on the main Src related signalling pathways – FAK, Akt, EGFR, Erk, Stat, etc – and cellular processes – proliferation, survival, migration, invasion, stemness and metabolism – should be carried out in the specific tumour model." (PMID 36217026, 2022). "We compared the expression of EGFR and CXCR4 in serum sEV with that in the primary tumor tissue assessed by IHC, which is a clinically used gold standard to examine the expression of marker proteins." (PMID 35269297, 2022). "There is huge of evidence that claims receptor tyrosine kinase (RTK): for instance, HER2 and EGFR, IGFIR, and hepatocyte growth factor receptor (HGFR) are tumor initiators in breast tissue." (PMID 35223101, 2022). "EGFR inhibition can increase MHC expression, enhance dendritic cell function, and increase T cell infiltration into the tumor." (PMID 36443704, 2022). "EGFR and RET tumor models in Drosophila reveal decreased tumor growth and increased survival when cytoneme formation is disrupted in neoplastic cells and surrounding tissue." (PMID 35119540, 2022). "PGE2 promotes tumor cell EMT and invasion by interacting with oncogenic signals, including epidermal growth factor (EGF) and epidermal growth factor receptor (EGFR)." (PMID 35936717, 2022). "EGFR was higher expressed in patients with vascular invasion; p-PI3K expression in Kazak was higher than that in Han; Ki-67 expression was higher in tumour size ≥ 3 cm." (PMID 36090016, 2022). "In tumor cells, PI3K is activated by several growth factors such as epidermal growth factor receptor (EGFR) and platelet-derived growth factor receptor (PDGFR)." (PMID 36555334, 2022). "Tumor driver genes in NSCLC patients have been uncovered one by one, including epidermal growth factor receptor (EGFR), mesenchymal lymphoma kinase (ALK), and receptor tyrosine kinase ROS proto-oncogene 1 (ROS1) mutants." (PMID 36499382, 2022). "Clinical trials were performed with imaging modalities using targets such as vascular endothelial growth factor (VEGF), epidermal growth factor receptor (EGFR) and prostate-specific membrane antigen (PSMA) in different tumor types." (PMID 36581931, 2022). "The highest tumor uptake was observed at 120 h (14.7% and 19.1% IA/g for DLD-1 (high EGFR expression) and HT-29 (high EGFR expression), respectively)." (PMID 36145664, 2022). "For instance, in glial cells, STAT3 exerts a tumor-suppressive effect with complete PTEN function, whereas in epidermal growth factor receptor (EGFR)vIII-positive tumors, it plays an oncogenic role, both of which are mediated by different signaling pathways." (PMID 36557902, 2022). "As both the EGFR/Ras/Raf/MAPK and the PI3K/Akt pathway are involved in autophagy, combinations of EGFR and PI3K/Akt pathway inhibitors can induce an autophagic response in tumor cells." (PMID 36551613, 2022). "BM progression is a unique disease progression pattern with insufficient response to anti-tumor drugs and poor prognosis because of the active blood–brain barrier (BBB); it accounts for approximately 40% of prior generation EGFR-TKI-resistant metastasis sites." (PMID 35785185, 2022). "EGFR-specific CAR-T cell have shown anticancer potential in lung cancer, and better safety and anti-tumor effect in phase I clinical trials of pancreatic cancer." (PMID 35935930, 2022). "Other tumour-specific ligands, such as epidermal growth factor (EGF), can bind to the receptor EGFR and induce the process of micropinocytosis, which enables nonspecific uptake of cancer-related cargoes." (PMID 36167539, 2022). "The link between EGFR/MAPK/ERK signalling cascade and its downstream activation of tumour cell proliferation has been well-established." (PMID 36333293, 2022).
tumor (continued). "In order to enhance the antitumor activity of CAR-T cells, some researchers also combined decitabine with EGFR-targeting CAR-T cells to conduct anti-bladder tumor studies, and the study found that the combination can enhance the tumor-specific killing of BC." (PMID 35860578, 2022). "We further tested this hypothesis in patients who were diagnosed with advanced EGFR-mutated NSCLC and treated with EGFR-TKIs by monitoring early dynamic changes of resistance-associated gene alterations during treatment using plasma circulating tumor DNA (ctDNA)." (PMID 35326664, 2022). "The recent study by Wu and colleagues demonstrated that the EGFR inhibitor, afatinib, in combination with FGFR inhibition with infigratinib, led to significant reduction in tumor growth." (PMID 36274097, 2022). "The activation and expression of the epidermal growth factor receptor (EGFR), which plays a role in tumor biology, are presumably influenced by zinc." (PMID 35216384, 2022). "Here, we demonstrate that activated T-cells (ATC) armed with anti-CD3 x anti-EGFR bispecific antibody increases TIL and mediate anti-tumor cytotoxicity while decreasing tumor cell viability." (PMID 35177811, 2022). "Epidermal growth factor receptor (EGFR), the receptor for EGF cell proliferation and signal transduction, is related to the inhibition of tumor cell proliferation, angiogenesis, tumor invasion, metastasis, and apoptosis." (PMID 35903247, 2022). "In the phase II ATLANTIC study, the investigators assessed the effect of durvalumab (anti-PD-L1) treatment as third-line or later treatment in three cohorts of patients with NSCLC defined by EGFR/ALK status and tumor expression of PD-L1." (PMID 35444951, 2022). "EGFRvIII CAR acted as an anchor to the tumor, whereas EGFR-targeted BiTE redirected both CAR T cells and bystander T cells to attack the heterogeneous tumor." (PMID 36059449, 2022). "Both EGFR and PI3K/AKT signaling pathways have been shown to induce NRF2 activation and tumor cell proliferation." (PMID 35806042, 2022). "The epidermal growth factor receptor (EGFR) is a transmembrane protein receptor endowed with tyrosine kinase activity, occupying an important position in cancer progression and tumour cell biology." (PMID 35801486, 2022). "As for the ErbB signaling pathway, identification of the role of ErbB (EGFR, HER2) in tumor radioresistance has led to attempts to sensitize tumors by inhibiting receptor signaling." (PMID 35845940, 2022). "For the isogenic tumor cell line pair UOK257, we observed that FLCNNEG cells were specifically more sensitive to EGFR inhibition than the FLCN-reconstituted cells." (PMID 35863698, 2022). "By binding to domain III of the extracellular domain of the epidermal growth factor receptor (EGFR), which is overexpressed on tumor cells, cetuximab competitively inhibits the binding of EGF and other ligands, preventing the dimerization of EGFR." (PMID 35076451, 2022). "The role of therapy-induced autophagy following dual targeting of the EGFR and PI3K/Akt pathway as an anti-tumor mechanism is still largely unclear in HNSCC." (PMID 36551613, 2022). "Despite the success of targeted therapy in EGFR mutant NSCLC, the heterogeneous outcomes suggest that the effects may not depend solely on EGFR-driven cancer cells, but may also be associated with the local tumor immune microenvironment and antitumor T cell responses." (PMID 35014626, 2022). "Significant correlations were observed between the expression of DDR1, EGFR, and SRC/BCR axis, indicating its active involvement in COAD [source: GEPIA; datasets, TCGA (tumor), GTEx (Normal)]." (PMID 35664781, 2022). "The results showed that KU55933 reduced IR-induced EGFR phosphorylation in CRC cell lines, inhibited tumor cell growth and sensitized tumor cells to IR, as well as decreased the efficiency of HR repair in IR-induced DSBs." (PMID 36230796, 2022).